PIM1 (Pim-1 proto-oncogene, serine/threonine kinase)
Diseases named in the same sentence as PIM1 in open-access papers (continued):
Sharing a sentence is not in itself a finding about the gene and the disease.
autoimmune disease (1 paper, 2026). A disorder resulting from loss of function or tissue destruction of an organ or multiple organs, arising from humoral or cellular immune responses of the individual to their own tissue constituents. "Previously, proviral integration site for Moloney-murine leukemia virus 1 (Pim1) was reported to be involved in various autoimmune diseases by mediating the proinflammatory effects of T cells." (PMID 41767599, 2026).
brucellosis (1 paper, 2024). Brucellosis is a bacterial infection that spreads from animals to people via unpasteurized dairy products or by exposure to contaminated animal products or infected animals. "The expression levels of multiple genes (e.g., PIM1, PIM3, KLF4) involved in the ‘negative regulation of cell apoptotic process’ were higher in brucellosis patients than in controls." (PMID 39135683, 2024).
carcinoids (1 paper, 2020). "The aim of this pilot study was to determine mRNA and protein levels of NEK2, PIM1, and PIM3 in a group of 49 patients with BP-NENs: 11 typical carcinoids, 5 atypical carcinoids, 11 large cell neuroendocrine carcinomas, 22 small cell lung carcinomas (SCLC)." (PMID 32504181, 2020).
clear-cell renal-cell carcinoma (1 paper, 2018). "However, to date, the potential regulatory roles and molecular mechanisms by which PIM1 affects the development and progression of cancers, including clear-cell renal-cell carcinoma (ccRCC), remain largely unknown." (PMID 29472550, 2018).
cognitive deficits (1 paper, 2016). "In conclusion, our data highlight the commercially available Pim1 inhibitor as a potential therapeutic to reduced AD-neuropathology and associated cognitive deficits by decreasing elevated pPRAS40 levels and increasing proteasome activity in the 3xTg-AD mouse model." (PMID 27412291, 2016).
colon adenoma (1 paper, 2014). An adenoma that arises from the colon. "To this end, we monitored PIM-1 expression inhuman colon adenomas by immunohistochemical staining." (PMID 25040935, 2014).
deep vein thrombosis (1 paper, 2024). "Several recent studies have associated the inhibition of the CXCR4/CXCL12 axis with a reduction in both arterial and venous thrombus formation, with increased circulating levels of CXCL12 and Pim-1 observed in deep vein thrombosis." (PMID 39062849, 2024).
diabetic nephropathy (1 paper, 2022). "It was also observed that hispidulin modulated multiple Pim1-interacted proteins such as NRAS and RAB18 to regulate the development of diabetic nephropathy." (PMID 34028657, 2022).
endometrial carcinoma (1 paper, 2022). A malignant tumor arising from the epithelium that lines the cavity of the uterine body. "Using multivariate COX regression analysis, two genes associated with endometrial carcinoma prognosis—PIM1 and BIRC5 were obtained, both of which were high-risk genes." (PMID 35672846, 2022). "To further confirm these results, we compared the expression of PIM1 and BIRC5 genes in the control and drug groups by q-PCR, and the mRNA levels of both PIM1 and BIRC5 were significantly reduced in 25uM puerarin compared to the control endometrial cancer cells." (PMID 35672846, 2022).
eosinophilic disorders (1 paper, 2023). "Additionally, blocking the Pim-1/NFIL3 axis or selective elimination of GR-mediated TA restores apoptosis in IL-5-activated eosinophils suggesting NFIL3’s role in treating eosinophilic disorders associated with steroid resistance." (PMID 37664635, 2023).
germ cell tumor (1 paper, 2016). A benign or malignant, gonadal or extragonadal neoplasm that originates from germ cells. "We found a correlation between PIM1/2 expression and VENTX, SOX15, UTF1, NANOG, POU5F1P4, POU5F1P3, and POU5F1B expression in male germ cell tumors." (PMID 27901106, 2016).
HIV-1 infection (1 paper, 2012). The type species of lentivirus and the etiologic agent of acquired immunodeficiency syndrome (AIDS). "Moreover, the perturbation of eIF4E, a critical regulator of other transcription or translation factors including Cyclin D1, and Pim-1, may also result in an inhibition of HIV-1 infection." (PMID 22808186, 2012).
hyperprolactinemia (1 paper, 2023). Abnormally high level of prolactin in the blood. "This increase may be explained by the observed hyperprolactinemia since prolactin and STAT5 are known transcriptional activators of CITED2, HSPA5 and PIM1." (PMID 36694114, 2023).
hypopharyngeal tumor (1 paper, 2022). "According to the results of multivariate analysis, the variables that were significantly associated with an increased risk of local recurrence after radiotherapy were hypopharyngeal tumor location, advanced local extension (cT3-4), and high PIM-1 expression." (PMID 34993612, 2022).
kidney cancer (1 paper, 2018). Primary or metastatic malignant neoplasm involving the kidney. "Taken together, these results clearly suggest that PIM1 is aberrantly overexpressed in human ccRCC tissues and cell lines and positively correlated with human kidney cancer progression." (PMID 29472550, 2018). "To further test PIM1 overexpression in kidney cancer, we utilised a panel of four human ccRCC cell lines (ACHN, 786-O, 769-P and OS-RC-2) and HK-2 cells (an immortalised proximal tubule epithelial cell line) to examine relative PIM1 mRNA expression by qRT-PCR." (PMID 29472550, 2018). "The median survival time of kidney cancer patients with high-PIM1 expression was significantly shorter than that of those with low-PIM1 expression." (PMID 29472550, 2018). "To verify that PIM1 overexpression promotes kidney cancer, we generated four ccRCC cell lines using both ACHN and 786-O cells to measure proliferation in vitro." (PMID 29472550, 2018). "Depletion of PIM1 suppressed the migration, invasion and angiogenesis behaviours of ccRCC cells in vitro, indicating that PIM1 may be a cancer-promoting protein in kidney cancer." (PMID 29472550, 2018).
liver fibrosis (1 paper, 2022). "First, target proteins (PTPN2 and PIM1) that have not been clearly reported to be related to liver fibrosis were excluded." (PMID 35517817, 2022).
lung fibrosis (1 paper, 2022). "Furthermore, inhibition of PIM1 has also been reported to enhance fibrosis resolution following bleomycin challenge in young mice, suggesting that PIM1 inhibition may represent an effective strategy to block persistent lung fibrosis and promote resolution." (PMID 35167499, 2022).
lupus erythematosus (1 paper, 2015). An autoimmune, connective tissue chronic inflammatory disorder affecting the skin, joints, kidneys, lungs, heart, and the peripheral blood cells. "Pharmacological inhibition of PIM-1 should therefore provide novel therapeutic options in diseases that respond to innate immune stimulation with subsequently increased B cell activity, such as lupus erythematosus or myasthenia gravis." (PMID 26555723, 2015).
lymphoid tumours (1 paper, 2025). "All of this argues that p.Ser97Asn and likely many of the other variants are indeed increasing PIM1 enzymatic activity as a possible driver of lymphoid tumours." (PMID 41152984, 2025).
myelofibrosis (1 paper, 2023). A partial or complete replacement of the bone marrow stroma by fibrous tissue. "PIM1 gene has been shown to be involved in myelofibrosis in mice model and its inhibitor TP-3654 or its ablation can inhibit myelofibrosis." (PMID 37814319, 2023).
myeloid malignancies (1 paper, 2025). "One of the differentially upregulated Stat5-target genes was Pim1, that is commonly found upregulated in JAK2-V617F polycythemia vera (PV) and other myeloid malignancies." (PMID 40841769, 2025).
nasopharyngeal carcinoma (1 paper, 2022). A carcinoma arising from the nasopharyngeal epithelium. "In nasopharyngeal carcinoma cell lines, PIM-1 inhibition decreased cell proliferation and migration capacity." (PMID 34993612, 2022).
neoplastic syndrome (1 paper, 2012). A broad classification for disorders in which the development of neoplasms typically occur in association with a characteristic set of signs or symptoms. "However, prolonged or constitutive elevation of Pim-1 levels can contribute to hyperproliferative or neoplastic syndromes, indicating that it is essential to restrict PIM1 expression." (PMID 22413002, 2012).
ovarian tumors (1 paper, 2017). "Analysis of human breast, endometrial or ovarian tumors from public databases revealed a variable subset of tumors overexpressing PIM1 or PIM2." (PMID 28938604, 2017). "Moreover, PIM1/2 were overexpressed in human breast, uterine and ovarian tumors, correlating with inflammatory features and stem cell markers." (PMID 28938604, 2017). "We also found that PIM1 and PIM2 are overexpressed in a subset of human female breast, endometrial and ovarian tumors and that this overexpression correlated with clear inflammatory features and stem cell markers." (PMID 28938604, 2017). "Therefore, we tested whether PIM1 and PIM2 expression is correlated with stem markers in human female breast, uterine and ovarian tumors." (PMID 28938604, 2017).
Peritoneal Fibrosis (1 paper, 2023). Disorder characterized by a wide range of structural changes in PERITONEUM, resulting from fibrogenic or inflammatory processes. "BAX, PIM1, AR, and others are involved in signaling pathways such as apoptosis, cell migration, and metabolism which also involved in peritoneal fibrosis." (PMID 37266145, 2023). "Among them, MMP2, BAX, ADORA3, HIF1A, PIM1, CA12, and ALOX5 exhibited higher expression in the peritoneum with encapsulating peritoneal sclerosis compared with those in the control, which might be crucial targets of baicalein against peritoneal fibrosis." (PMID 37266145, 2023).
pterygium (1 paper, 2022). A wedge-shaped fibrovascular lesion arising from the bulbar conjunctiva and extending to the cornea. "In active pterygium, genes involved with immune and inflammatory response (CXCL9 and PLA2G2D), angiogenesis (SERPINB5 and BM4), keratinization (DSG1), response to UV light (TYR) and negative regulation of apoptotic process (PIM1) are up regulated in relation to atrophic pterygium." (PMID 34997134, 2022).
rectal tumors (1 paper, 2020). "Moreover, high expression levels of PAI1 are associated with increased metastasis and invasion of rectal tumors in this cohort and TCGA database, respectively, which is correlated with EMT-associated and drug target genes expression, including PDGFRa, PDGFRb, FYN, PIM1 and BRAF." (PMID 32344898, 2020).
sarcoma (1 paper, 2014). A usually aggressive malignant neoplasm of the soft tissue or bone. "Consistent with this hypothesis, PIM1 (a client protein of HSP90AA1 that affects sarcoma growth and bone invasion) is rapidly decreased in the 2-24a/Cu-treated cells." (PMID 25167922, 2014). "PIM1 is a client protein of HSP90AA1 in oncogenesis, and plays important roles in sarcoma growth and bone invasion." (PMID 25167922, 2014).
seminoma (1 paper, 2016). A radiosensitive malignant germ cell tumor found in the testis (especially undescended), and extragonadal sites (anterior mediastinum and pineal gland). "Interestingly, seminoma showed the highest levels of PIM1/2 kinase overexpression in the highest percentage of tumors." (PMID 27901106, 2016).
Sézary Syndrome (1 paper, 2014). "Furthermore, PIM1 and, again, especially PIM2, but not PIM3 expression was increased in a panel of 8 PTCL cell lines and primary tumoral T cells from 5 Sézary Syndrome patients relative to normal T cells from 3 healthy donors." (PMID 25386922, 2014).
skin cancer (1 paper, 2017). "PIM-1 was identified as a proto-oncogene in many cancers, including pancreatic, prostate, gastric and skin cancer and leukemia, but its underlying mechanism of action in HCC remains to be established." (PMID 29093516, 2017).
Stress urinary incontinence (1 paper, 2025). Involuntary urine leakage synchronous with exertion, or actions such as sneezing, or coughing. "This study aims to explore the contribution of PIM1 kinase-mediated cellular senescence to the pathogenesis of stress urinary incontinence (SUI) and to assess the therapeutic potential of inhibiting PIM1." (PMID 41223182, 2025).
T-cell neoplasms (1 paper, 2024). "Overall, we revealed PIM1 as a potential therapeutic target for the leukemogenic effects mediated by JAK/STAT pathway mutations in precursor T-cell neoplasms." (PMID 39033228, 2024).
thymic lymphomas (1 paper, 2011). "In contrast to thymic lymphomas the multicentric, non-T-cell tumors in our collection demonstrated no involvement of c-myc, flvi-2, fit-1 or pim-1 loci as measured by Southern blot analysis for evidence of FeLV proviral insertion or transduction." (PMID 21994802, 2011).
thymoma (1 paper, 2014). A neoplasm arising from the epithelial cells of the thymus. "When AKR mice were treated with N-methyl-N-nitrosourea (MNU), tumor development started as early as 3 months of age, and pim1 and c-myc gene rearrangements due to proviral integration were observed in several of the resulting thymomas." (PMID 24860787, 2014). "Spontaneous tumors in AKR mice (which usually develop at 6 month of age) are distinct, and the development of thymomas that contain proviral integrations at the pim1 locus in the MNU-treated AKR mice involves the cooperation between the chemical carcinogen and endogenous murine leukemia virus." (PMID 24860787, 2014).
toxoplasmosis (1 paper, 2026). A parasitic disease contracted by the ingestion or fetal transmission of toxoplasma gondii. "Collectively, the research emphasizes the role of PIM1 in the proliferation of T. gondii during infection and highlights the therapeutic potential of PIM1 inhibition in the fight against toxoplasmosis." (PMID 41557744, 2026). "The inhibition of PIM1 activity presents a promising avenue for the development of targeted therapies against toxoplasmosis, with potential implications for the treatment of other diseases influenced by this protozoan parasite." (PMID 41557744, 2026). "The potential therapeutic application of AZD1208, a PIM1 small molecule inhibitor, in treating toxoplasmosis has been brought to light by these findings." (PMID 41557744, 2026). "Thus, targeting PIM1 in combination therapy is particularly rational for treating toxoplasmosis in cancer patients." (PMID 41557744, 2026). "However, the role of PIM1 in vivo during T. gondii infection and the treatment of toxoplasmosis by AZD1208 have been rarely studied." (PMID 41557744, 2026).
uterine tumors (1 paper, 2017). "We also found a percentage of mammary gland and uterine tumors in PIM1 transgenic mice." (PMID 28938604, 2017).
Vogt-Koyanagi-Harada disease (1 paper, 2022). A bilateral, chronic, diffuse granulomatous panuveitis typically characterized by serous retinal detachment and frequently associated with neurological (meningitis), auditory, and dermatological alterations. "PIM1 expression in PBMCs from patients with MS showed similar alterations to that in patients with VKH disease." (PMID 36195600, 2022).
cancer (188 papers, 2004 to 2026). A tumor composed of atypical neoplastic, often pleomorphic cells that invade other tissues. "Several studies also show that Pim1 can indirectly regulate Akt phosphorylation in various cancers, and that this associates with improved survival and proliferation." (PMID 40164682, 2025). "Overexpression of PIM-1 has been linked to cancer initiation and progression through three significant mechanisms: inhibiting apoptosis, promoting cell proliferation, and promoting genomic instability." (PMID 39521748, 2025). "PIM1 was found to be associated with the drug resistance abilities of cancer cells by interacting with other cancer-related proteins." (PMID 40649898, 2025). "The proviral integration site for the Moloney murine leukemia virus (PIM) kinases, including Pim-1, Pim-2, and Pim-3, have been implicated in cancer progression as oncogenic serine/threonine kinases." (PMID 39507762, 2024). "Overexpression of PIM-1 is linked to poor prognosis and therapy resistance in various cancers, including hematological malignancies and solid tumors." (PMID 39434908, 2024). "The heightened activity of PIM-1 in these cancers is linked to various oncogenic processes, such as promoting cell survival, enhancing cell cycle progression, and inhibiting apoptosis." (PMID 39434908, 2024). "Based on the earlier data of Pim1 kinase protein structure and the importance of bis-thiazole potential cytotoxicity, this study aimed to design novel bis-thiazole derivatives as preferential Pim1 inhibitors to treat the underlying cancer types." (PMID 36728746, 2023). "Further study for the molecular mechanism of GBP5-associated EGFR, STAT1, chemotherapy resistance-associated cancer stemness markers, and PIM1 is warranted in OSCC." (PMID 34439200, 2021). "High expression of proviral integration site for Moloney murine leukemia virus-1 (PIM-1), a serine/threonine kinase, is associated with many cancers." (PMID 28851457, 2017). "A recent report indicated that CamKII inhibitors, directly or indirectly, inhibits several other kinases, including Pim1, a kinase that has been associated with genomic instability in cancers." (PMID 24982612, 2014). "Our model supports the role for Pim1, a kinase that has been associated with genomic instability in cancers, in genomic instability in Cx32 mutations." (PMID 24982612, 2014). "Pim-1 plays a pivotal role in tumorigenesis and overexpression of it has been implicated in several cancers." (PMID 25551195, 2014). "In this study we selected nsSNPs resulting in Pim-1 variants that are expressed in cancer tissues and reported in SNP database." (PMID 23755147, 2013). "This phenomenon caught our interest, and we have found that higher levels of pim-1 expression in cancer-associated stroma were associated with higher DFS and OS." (PMID 24116137, 2013). "Many cancer types show high expression levels of Pim kinases and particularly Pim-1 has been linked to the initiation and progression of the malignant phenotype." (PMID 23755147, 2013). "Provirus integration site for Moloney murine leukemia virus (pim-1) is a proto-oncogene that is linked to the development and progression of several cancers." (PMID 24116137, 2013). "Our data further indicated that pim-1-positive cancer-associated tumor stroma cells were protective to the host, but the exact mechanism of their action still remains to be elucidated." (PMID 24116137, 2013). "The researchers also tested a drug called SGI-1776, which inhibits Pim1, and found that it could protect against bone loss in conditions such as inflammation and cancer." (PMID 40164682, 2025). "Elevated expression of PIM-1 has been associated with poor prognosis in several types of cancer." (PMID 34993612, 2022).